KDM6A (lysine demethylase 6A)
Diseases named in the same sentence as KDM6A in open-access papers (continued):
Sharing a sentence is not in itself a finding about the gene and the disease.
COVID-19 (1 paper, 2021). A disease caused by infection with severe acute respiratory syndrome coronavirus 2. "Although these studies are compelling in linking KDM6A to immune responses, it is still questionable whether it has a role in immune responses against COVID-19." (PMID 33469152, 2021).
endothelial dysfunction (1 paper, 2026). In vascular diseases, endothelial dysfunction is a systemic pathological state of the endothelium (the inner lining of blood vessels) and can be broadly defined as an imbalance between vasodilating and vasoconstricting substances produced by (or acting on) the endothelium. "Müller cell-specific Kdm6a overexpression exacerbated DR vascular pathology, while in vitro co-cultures confirmed that KDM6A in Müller cells induces endothelial dysfunction." (PMID 42049713, 2026).
ependymoma (1 paper, 2022). A WHO grade II, slow growing tumor of children and young adults, usually located intraventricularly. "For instance, the hypoxic metabolism of posterior fossa A ependymoma generates intermediary products that favor higher levels of H3K27ac (acetyl-CoA) and lower levels of H3K27me3 (α-ketoglutarate, which stimulates the activity of the H3K27 demethylases KDM6A and KDM6B)." (PMID 36371348, 2022).
fibroepithelial polyp (1 paper, 2025). A polypoid lesion composed of fibrous tissue and epithelium. "The other mutations found in our case (DNMT3A, C8B, TET2, SDHA, ARID1B, NOTCH1, OR5L1, and KDM6A) do not have a known association with the formation of fibroepithelial polyps." (PMID 40936011, 2025).
glomerular disease (1 paper, 2019). "Conversely, pharmacological inhibition of two demethylating enzymes KDM6A (also called UTX) and KDM6B (also called JMJD3), which specifically demethylate H3K27 dimethylation (H3K27me2) and H3K27 trimethylation (H3K27me3), attenuated glomerular disease." (PMID 30948420, 2019).
head and neck squamous cell carcinoma (1 paper, 2025). A squamous cell carcinoma that arises from any of the following anatomic sites: lip and oral cavity, nasal cavity, paranasal sinuses, pharynx, larynx, and salivary glands. "However, the regulatory mechanisms controlling KDM6A activity in head and neck squamous cell carcinoma (HNSCC) are not well defined." (PMID 41184251, 2025).
Hutchinson-Gilford progeria (1 paper, 2020). "Metformin restores the global levels of H3K27me3 in fibroblasts of aged individuals or from patients with premature aging syndromes such as Hutchinson-Gilford progeria or Werner syndrome, likely by directly targeting the H3K27me3 demethylase KDM6A/UTX." (PMID 32443566, 2020).
idiopathic thrombocytopenic purpura (1 paper, 2021). "Interrogation of bone marrow samples from newly diagnosed CML patients against control patients with idiopathic thrombocytopenic purpura showed an increase in KDM6A mRNA expression associated with CML." (PMID 33456567, 2021).
invasive carcinoma (1 paper, 2025). A carcinoma that is not confined to the epithelium, and has spread to the surrounding stroma. "The density of KDM6A-pSer829 was significantly higher in invasive carcinoma as compared to normal mucosa." (PMID 41184251, 2025).
kidney damage (1 paper, 2022). "Under diabetic conditions, KLF10 induces KDM6A expression, causing proteinuria and irreversible kidney damage." (PMID 36012674, 2022).
malignant pleural mesothelioma (1 paper, 2025). A malignant neoplasm that arises from mesothelial cells in the pleura and shows a diffuse growth pattern. "Dr. Cregan reported that preliminary testing of GSK-J1 on NCI-H226 cell proliferation showed that it could inhibit the growth of malignant pleural mesothelioma (MPM) cells with KDM6A mutations." (PMID 40297816, 2025).
mycobacterial infections (1 paper, 2022). "Of 15 prioritized in this study genes, four genes, namely GBP2, HEATR3, PPP1R9B and KDM6A, exhibited an elevated transcriptional level in whole blood, spleen or EBV-transformed lymphocytes, thus lending additional support to their role in increasing susceptibility to mycobacterial infections." (PMID 36338958, 2022).
myocardial infarction (1 paper, 2024). Gross necrosis of the myocardium, as a result of interruption of the blood supply to the area, as in coronary thrombosis. "Moreover, the expression of HDM KDM6A markedly elevates in myocardial infarction tissues, and blocking KDM6A could prevent sodium-calcium exchange and cardiomyocyte apoptosis in myocardial infarction rats." (PMID 38584203, 2024).
nephrocalcinosis (1 paper, 2025). Nephrocalcinosis is a disorder that occurs when too much calcium is deposited in the kidneys. "One study indicated that 2 of 61 patients with KDM6A mutations had nephrolithiasis/nephrocalcinosis." (PMID 40437108, 2025).
neuropathy (1 paper, 2021). A disorder affecting the nervous system that manifests with pain, tingling, numbness, and/or muscle weakness. "In the light of the involvement of PK2 in BTZ-induced neuropathy, these observations suggest the possible involvement of KDM6A in the epigenetic mechanisms underlying this neuropathic pain condition." (PMID 34769347, 2021).
obstructive uropathy (1 paper, 2023). "In the present study, we explored the expression patterns of Kdm6a in kidney tubule epithelial cells and the effects of Kdm6a knockout from tubule epithelial cells in mice under sham-operated conditions and with obstructive uropathy caused by UUO." (PMID 37655466, 2023). "We began our studies by examining the expression patterns of Kdm6a in the kidneys of male mice after UUO, a well-established model of obstructive uropathy that causes inflammation and fibrosis, central determinants of the progression of CKD to end-stage kidney disease." (PMID 37655466, 2023). "The absence of tubule cell KDM6A in male mice causes relatively subtle transcriptional and phenotypic changes that, under conditions of obstructive uropathy, are characterized by increased kidney inflammation." (PMID 37655466, 2023).
pulmonary edema (1 paper, 2020). Accumulation of fluid in the lung tissues causing disturbance of the gas exchange that may lead to respiratory failure. "At 8 weeks follow up, PTFE-treated mice show increased ventricular expression of the novel hypoxia marker KDM6A, mild systolic and diastolic contractile dysfunction, signs of cardiac eccentric hypertrophy and pulmonary edema, that were accompanied by CaMKII overexpression." (PMID 33301470, 2020).
pulmonary stenosis (1 paper, 2024). "The anatomic types of CHDs associated with KDM6A variants included septal defects, hypoplastic right ventricle, pulmonary stenosis, and aortic abnormalities (e.g., abnormal shape, subaortic membrane, bicuspid valve, and coarctation)." (PMID 38667491, 2024).
renal dysplasia (1 paper, 2014). Renal dysplasia is a form of renal malformation in which the kidney(s) are present but their development is abnormal and incomplete. "Authors observed a high frequency of somatic mutations in chromatin modifiers, particularly KDM6A, in AA-UTUC, demonstrated the sufficiency of AA to induce renal dysplasia in mice, and reproduced the AA mutational signature in experimentally treated human renal tubular cells." (PMID 24949484, 2014).
Ta (1 paper, 2020). "The lysine demethylase 6A (KDM6A) is mutated in 60% of low-grade Ta tumors and inhibits H3K27 methyltransferase EZH2." (PMID 32784716, 2020).
teratocarcinoma (1 paper, 2025). A germ cell tumor characterized by the presence of an embryonal carcinoma component and a teratoma component. "For instance, it upregulates HOX genes during the differentiation of teratocarcinoma and embryonic stem cells, suggesting that KDM6A functions both through its demethylase activity and structural role in chromatin regulation." (PMID 40659611, 2025).
thymic adenocarcinoma (1 paper, 2017). "Recurrent mutations in chromatin remodeling genes were reported in thymic carcinomas, but no mutation in chromatin remodeling genes (SETD2, KDM6A, MLL2, and MLL3) was found in thymic adenocarcinoma." (PMID 28506304, 2017).
thyroglossal duct cyst (1 paper, 2019). A congenital benign cyst arising from the remnants of the thyroglossal duct. "We did observe some developmental anomalies in adult Kdm6a progeny, including ectopic tissue rests, tail kinks, scoliosis, and a thyroglossal duct cyst." (PMID 30963999, 2019).
thyroid (1 paper, 2024). "To clarify the role of KDMs in thyroid tumorigenesis, we next examined the mRNA expressions of KDM5C, KDM5D, and KDM6A by RT-PCR in a set of normal thyroid and tumor tissue samples from 77 patients, who underwent surgery for thyroid nodules." (PMID 38610938, 2024).
Ureteral obstruction (1 paper, 2023). Obstruction of the flow of urine through the ureter. "We initially observed an increase in tubule cell Kdm6a mRNA in male mice with unilateral ureteral obstruction (UUO)." (PMID 37655466, 2023).
Weaver syndrome (1 paper, 2024). Weaver syndrome (WVS) is a rare, multisystem disorder characterized by tall stature, a typical facial appearance (hypertelorism, retrognathia) and variable intellectual disability. "An EZH2 missense mouse model of Weaver syndrome exhibits skeletal overgrowth, excess osteogenesis, and a characteristic transcriptomic profile that is reversed with a KDM6A/6B inhibitor." (PMID 38015625, 2024).
‐invasive urothelial bladder carcinoma (1 paper, 2022). "They reported that the proportion of KDM6A mutations in non‐muscle‐invasive urothelial bladder carcinoma was 45%, muscle‐invasive tumors was 28%, and in tumors of unknown stages was 28%." (PMID 36052737, 2022).
tumor (229 papers, 2012 to 2026). "Inactivation of KDM5C or KDM6A through deletion or mutation leads to epigenetic changes in the targeted transcription factor circuitry, disrupting tumor differentiation and promoting tumor cell proliferation." (PMID 41301905, 2025). "Future studies will incorporate functional assays using BTC-derived organoids and CRISPR-based editing to determine how KDM4B, KDM5C, and KDM6A mutations contribute to epigenetic dysregulation and tumor initiation." (PMID 41301905, 2025). "Together, these findings demonstrate how loss of KDM6A mutations creates an immunologically cold tumor microenvironment through both cellular depletion and pathway suppression." (PMID 40693457, 2025). "A recent study found that KDM6A mutation downregulated specific signaling pathways that are involved in the immune system and attenuated the tumor immune response." (PMID 39941725, 2025). "Beyond its general tumor-suppressive role, KDM6A loss in BC has been shown to attenuate the anti-tumor immune response." (PMID 40918525, 2025). "Tumors with KDM6A mutations tend to have fewer tumor-infiltrating lymphocytes (especially CD8+ T cells) and a microenvironment skewed toward immune tolerance." (PMID 40918525, 2025). "KDM6A functions as a tumor suppressor and is frequently mutated in high-grade, invasive bladder cancers." (PMID 39744495, 2025). "An example of a targetable frequent molecular aberration is the disruption of KDM6A, a key histone lysine demethylase, causing an epigenetic ‘switch’ to disrupt urothelial differentiation and promote neoplasia." (PMID 38540132, 2024). "The impact of KDM6A deficiency on the tumor microenvironment (TME) in PDAC has been recently described." (PMID 38791111, 2024). "Loss of nuclear KDM6A expression was associated with increased KDM6A expression in the cytoplasm of tumor cells." (PMID 38610938, 2024). "Recently, it was shown that loss of HNF1A, a homeodomain transcriptional regulator that recruits KDM6A to genomic binding sites, can phenocopy KDM6A loss and produce a sarcomatoid tumor morphology in conjunction with Kras mutation in mouse pancreas." (PMID 37538977, 2023). "KDM6A [also known as ubiquitously transcribed tetratricopeptide repeat on chromosome X (UTX)], a tumor-suppressor gene encoding histone 3 lysine 27 (H3K27) demethylase, plays a vital part in determining cell fate and cell differentiation during development." (PMID 36937322, 2023). "For example, HNF1A exerts its tumor-suppressive effect by forming a complex with lysine-specific demethylase 6A, encoded by the KDM6A gene, to inhibit the oncogenic pathway in a mouse acinar cell line." (PMID 35328643, 2022). "We also noticed that although KDM6A mRNA expression and methylation exhibited heterogeneities within and across individual tumours, the loss of KDM6A copy number remained consistent." (PMID 35061935, 2022). "As our results revealed that Kdm6a-deficient tumours exhibit a high mTORC1 activity, we next tested if they are particularly sensitive to pharmacological mTORC1 inhibition." (PMID 34509979, 2022). "Both neoplasms showed a loss of E-cadherin and conserved expression of KDM6A; BAP1 showed a heterogeneous staining pattern in the first tumor and conserved expression in the second neoplasm." (PMID 35359182, 2022). "KDM6A/UTX Mutations in domains other than the SET domain are seen in cancer suggesting a role of these domains in the tumour suppressor function." (PMID 35406676, 2022). "Kdm6a-deficient tumours showed hyperactivation of mTORC1 signalling, whereas endogenous Kdm6a re-expression by inducible RNA-interference in established Kdm6a-deficient tumours diminished mTORC1 activity resulting in attenuated tumour progression." (PMID 34509979, 2022). "KDM6A gene was mutated within a tumor that originated within corpus callosum with similar gene expression pattern being elevated within the midline structures of corpus callosum, cingulum bundle, and thalamus." (PMID 34257334, 2021).
tumor (continued). "Tumor Immune Estimation Resource (TIMER) analysis showed that KDM6A mutation was associated with a lower number of TIICs." (PMID 34051747, 2021). "KDM6A (also known as UTX) is an H3K27me3 histone demethylase that functions as a tumor suppressor gene, targeted by loss-of-function mutations in approximately 5–15% of T-ALLs." (PMID 34440292, 2021). "Analyses of tumour-associated genes showed frequent loss of KDM6A expression in several cancers, including BC, B-cell lymphoma, lung squamous cell carcinoma, head and neck squamous cell carcinoma, pancreatic adenocarcinoma, and renal papillary cell carcinoma." (PMID 34051747, 2021). "This idea is reinforced by findings that epigenetic therapy of KDM6A-deficient UBCs caused NK cell attack and tumor regression in a preclinical model." (PMID 34768683, 2021). "Using the CIBERSORT algorithm, Tumor Immune Estimation Resource site, and Gene Set Enrichment Analysis, we found that KDM6A mutation downregulated nine signalling pathways that participate in the immune system and attenuated the tumour immune response." (PMID 34051747, 2021). "Nevertheless, KDM6A cannot be perceived solely as a tumor suppressor, as KDM6A is found to have close association with genesis and progression of different cancers." (PMID 34950587, 2021). "Tying this result to its H3K27me3 demethylase activity, loss of KDM6A leads to accumulation of H3K27me3 at the promoters of putative tumor suppresser genes, including FBXW7 and RBBP6." (PMID 33003334, 2020). "Analyses of matched diagnosis and relapse specimens from individuals with KDM6A mutations showed an outgrowth of the KDM6A mutated tumor population at relapse." (PMID 31201358, 2020). "The protein UTX encoded by gene KDM6A has the function of catalyzing the demethylation of histone H3, and is involved in cell differentiation and tumor suppression." (PMID 32957974, 2020). "GLUT1 expression was strongly upregulated in KDM6A‐mutated tumours (both primary and metastatic) compared with KDM6A‐proficient tumours." (PMID 30306561, 2019). "KDM6A has been mechanistically implicated as a tumor suppressor in ALL, AML, and lung cancer, and also plays important developmental roles, especially in the heart and blood." (PMID 30963999, 2019). "The high prevalence of evidently deleterious KDM6A mutations throughout all stages and molecular subtypes of UC suggests an important tumor-suppressive function of UTX." (PMID 30987376, 2019). "We conclude that repeated loss of Kdm6a in the male germ line is required to maintain the intergenerational tumor susceptibility phenotype." (PMID 30963999, 2019). "Overall, these data indicate that activation of NK cells is one of the potential anti-tumor mechanisms in EZH2 inhibitor-treated HT1376 xenografts with KDM6A and SWI/SNF family member mutations." (PMID 30692641, 2019). "Many commonly mutated large tumour suppressor genes (e.g. KDM6A, KMT2D) with SMs widely distributed across the gene were unsuitable for inclusion." (PMID 31077629, 2019). "Because KDM6A functions primarily as a chromatin regulator, these studies imply that the epigenetic sequelae of KDM6A loss contribute to tumor initiation or progression." (PMID 30963999, 2019). "Both patients were hemizygous for the mutations as KDM6A is located on chromosome X. The presence of tumor suppressor genes on the chromosome X has been used to explain the imbalanced male/female sex ratio in cancers." (PMID 29989027, 2018). "In particular, they found that KDM6A, a histone demethylase already described as a tumor suppressor gene, was more frequently mutated across all male cancers." (PMID 29846646, 2018). "Of particular note is that BLCA is uniquely affected by KDM6A NMD-elicit mutations when compared with other tumour types." (PMID 28649990, 2017).